CXCL10 (C-X-C motif chemokine ligand 10)
Diseases named in the same sentence as CXCL10 in open-access papers (continued):
Sharing a sentence is not in itself a finding about the gene and the disease.
Sepsis (continued). "Nevertheless, as advocated for sepsis, immune profiling (including CXCL10 measurement) may serve for the selection of patients that could be eligible for immunotherapy." (PMID 33138839, 2020). "Indeed, type I IFN acts on hematopoietic cells and is required for survival in a mouse CLP-based sepsis model by increasing CXCL10 production, recruiting neutrophils and macrophages, and stimulating phagocyte functions." (PMID 29209091, 2017). "CXCL10, on the other hand, reduces survival in sepsis and contributes to the pathology of sepsis." (PMID 28852269, 2017). "We deduced that NEAT1 may be involved in the immune response in sepsis based on the close relationships between IL-6 and CXCL10 cytokines and the inflammatory response in sepsis." (PMID 29463949, 2017). "Increased HLA-DR, CCR5, and CXCL10 expression has been implicated in the pathogenesis of key causes of infant mortality in Africa, including HIV, lower-respiratory infections, sepsis, encephalopathy, and meningitis." (PMID 29312338, 2017). "Thus, CXCL10 in combination with other cytokines such as TNF are potential biomarkers for sepsis as a consequence of pyometra progression and also as targets in anti-inflammatory therapy in pyometra." (PMID 26222498, 2015). "However, further work is needed to determine how CXCL10 facilitates the pro-inflammatory functions of innate lymphocytes during severe sepsis." (PMID 24890566, 2014). "Studies were undertaken to determine whether blockade of CXCL10 alters survival during CLP-induced sepsis." (PMID 24890566, 2014). "Initial studies were undertaken to characterize the progression of sepsis in our model and determine whether evidence of sepsis was present at the time of anti-CXCL10 IgG treatment." (PMID 24890566, 2014). "In addition, the benefits of CXCL10 blockade were evident when anti-CXCL10 IgG was administered at 6 hours after the initiation of sepsis." (PMID 24890566, 2014). "Long-lived blockade of CXCL10 function could be deleterious to mounting effective downstream anti-microbial responses in patients with sepsis as demonstrated by the studies of Kelly-Scumpia and colleagues." (PMID 24890566, 2014). "Studies were undertaken to assess whether initiation of CXCL10 blockade after the onset of sepsis would improve survival." (PMID 24890566, 2014). "The present studies show that CXCL10-deficient mice are resistant to CLP-induced septic shock and more directly support a cause-and-effect relationship between CXCL10 and the pathogenesis of sepsis." (PMID 24890566, 2014). "CXCL10 has been shown to serve as a useful biomarker in human sepsis." (PMID 24890566, 2014). "CXCL10 blockade was initiated prior to or after the onset of sepsis." (PMID 24890566, 2014). "The improvement in survival observed when mice were treated with anti-CXCL10 IgG at 6 hours after CLP was particularly compelling because mice showed clinical signs of sepsis such as hypothermia, metabolic acidosis, systemic inflammation and bacteremia at the time of treatment." (PMID 24890566, 2014). "Additionally, using an ROC curve analysis, the plasma levels of IL-1β, IL-7, IL-12, IL-1RA, RANTES/CCL5, MIP1B/CCL4 and IP10/CXCL10 could help differentiate children with sepsis from both clinical malaria and febrile controls." (PMID 35811678, 2022). "A principal component analysis and a receiver operator characteristic curve analysis, identified seven potential biomarkers; IL-1β, IL-7, IL-12, IL-1RA, RANTES/CCL5, MIP1β/CCL4 and IP10/CXCL10 that could discriminate children with sepsis from clinical malaria and other febrile conditions." (PMID 35811678, 2022). "In addition, CXCL10 blockade could serve as a therapeutic target during acute septic shock, as treatment with anti-CXCL10 IgG and antibiotics was effective in improving survival when administered at 2 or 6 hours after the onset of sepsis." (PMID 24890566, 2014). "• CXCL10 could serve as a therapeutic target during the acute phase of sepsis." (PMID 24890566, 2014).
Sepsis (continued). "In both neonatal mouse sepsis model and septic preterm infants, CCL3, CCL7, and CXCL10 were similarly up-regulated in blood and brain, promoting neutrophil migration across the BBB and exacerbating brain inflammation." (PMID 40254577, 2025). "Further analysis demonstrated that SFT2D1 inhibition significantly decreased the expression levels of key inflammatory cytokines CXCL10 and IL-6 (P < 0.05), suggesting a role for SFT2D1 in promoting the inflammatory response in sepsis." (PMID 40370519, 2025). "The results showed that the levels of Tnfα, IL-1β, CXCL2, CXCL10, CCL2, and CCL3 increased significantly in response to sepsis sEVs compared with healthy sEVs." (PMID 38910259, 2024). "Children with sepsis had significantly higher levels of IL-1β, IL-12 and IL-17A compared to febrile controls but lower levels of MIP1-β/CCL4, RANTES/CCL5 and IP10/CXCL10 when compared to children with malaria and febrile controls." (PMID 35811678, 2022). "Relative to sepsis controls, patients with HBD + DIC were characterized by increased expression of ferritin, IL-18, sCD163, sCD25, IL-6, and CXCL10, consistent with a biomarker signature of macrophage activation." (PMID 35190900, 2022). "For distinguishing between sepsis from febrile controls, both CCL5 (0.82, p<0.01) and CXCL10 (0.82, p<0.001) showed the greatest potential in differentiating the two groups." (PMID 35811678, 2022). "While IL-2, CXCL10, and TNF-α contribute to the pathogenesis of sepsis, IL-7, IL-10, GCSF, MCP1, M1P1A are likely elevated as an endogenous attempt to combat sepsis." (PMID 32973504, 2020). "For the chemokines, CCL2 and CCL3 levels were elevated in the middle sepsis phase (12 h), while CCL5, CXCL9, and CXCL10 levels were significantly increased in the late phase." (PMID 31354717, 2019). "They further reported that the vulnerability can be reversed by treatment with CXCL10 and concluded that CXCL10 is an important regulator of antimicrobial function during low-severity CLP-induced sepsis in adult mice." (PMID 24890566, 2014). "The up-regulation of TNF-α, IL-1α, IL-1β, CXCL-10, SOCS3, IL-10 at 1 and 2 h in the present study was similar to that observed in blood profiles of sepsis patients at early stages." (PMID 23009705, 2012). "The mechanism of action of LSECs in sepsis is complex and diverse, involving multiple aspects such as the TLR4 signaling pathway, PD-L1-mediated immune regulation, the secretion of cytokines like IL-6 and CXCL10, and the regulation of Tregs." (PMID 40072101, 2025). "Downstream induction of CXCL9 (but not of CXCL10 and 11) occurring in a subset of patients with high IFNγ levels has been shown to correlate with the hyper-inflammatory phenotype of sepsis." (PMID 40762872, 2025). "While the CXCR3 ligand CXCL10 was shown before to correlate with severity in sepsis, in the present study concentrations of CXCL10 were lower in non-survivors within 30 days." (PMID 38430552, 2024). "High serum levels of CXCL10, IL-6, IL-10, TNF and IL-8 were reported in a canine sepsis model." (PMID 26222498, 2015). "That finding indicates that CXCL10 alone is not responsible for NK cell trafficking during CLP-induced sepsis, which is not surprising, given the redundancy of CXCR3 ligands." (PMID 24890566, 2014). "Furthermore, high CXCL10 concentrations correlate with the development of physiologic dysfunction and death in the CLP model of sepsis." (PMID 24890566, 2014). "• CXCL10 contributes to the activation of NK cells during the acute phase of sepsis but does not act alone to facilitate NK cell trafficking." (PMID 24890566, 2014). "Thus, targeting the chemokine axes CXCL9, CXCL10, which are involved in T and NK cell mobilisation, might be helpful to treat COVID19 as previously found in experimental sepsis." (PMID 34987646, 2022). "However, the functional importance of CXCL10 in the pathogenesis of severe sepsis has not been ascertained." (PMID 24890566, 2014).
Sepsis (continued). "She reported that applied OMVs from sepsis sepsis-inducing bacteria in contrast to non-sepsis sepsis-inducing bacteria significantly reduced the activity of RNase1 and promoted endothelial cell activation, as indicated by increased IL-8, CXCL10, ICAM-1, and IL-1β expression." (PMID 39697663, 2021). "Other immune markers deregulated in sepsis, such as CD16 or CD206, as well as the anti-inflammatory cytokine IL-10 and the cytokine CXCL-10, did not exhibit a clear pattern." (PMID 37047205, 2023). "The observed pattern mirrors the biphasic immunopathology seen in sepsis, where MASLD patients exhibited higher baseline levels of IL17A, IL-23, IL-33, CXCL10 and TGF-β1, yet experienced steeper declines in in IL-10, IL-23, CXCL10 and TGF-β1 in comparison to non-MASLD counterparts." (PMID 40869413, 2025).
vitiligo (81 papers, 2015 to 2025). Generalized well circumscribed patches of leukoderma that are generally distributed over symmetric body locations and is due to autoimmune destruction of melanocytes. "Our research findings robustly confirm a bidirectional positive causal relationship between CXCL10 and vitiligo." (PMID 38660673, 2024). "The JAK-STAT pathway is activated with IFN-γ as the crucial cytokine and Th1-associated chemokines such as CXCL9 and CXCL10 recruit immune cells towards vitiligo skin." (PMID 39274437, 2024). "Furthermore, increased serum levels of CXCL10 were associated with the clinical severity of vitiligo and decreased with disease stabilisation in response to effective treatment." (PMID 36675078, 2023). "Moreover, key mediators such as interferon-γ (IFN-γ), C-X-C chemokine ligand 9 (CXCL9) and 10 (CXCL10), as well as interleukin-15 (IL-15) are also implicated in etiology of vitiligo." (PMID 35884944, 2022). "Furthermore, IFIH1, encoding intracellular virus sensor MDA5, has been identified as a vitiligo susceptibility gene capable of inducing secretion of CXCL10 and CXCL16 from keratinocytes and inducing infiltration of CD8+ T cells in vitiligo." (PMID 33936032, 2021). "In addition, the previously reported vitiligo activity-associated markers including CXCL10 were also detected in each patient." (PMID 34977005, 2021). "Further, our results demonstrated an inverse relationship between vitiligo lesional duration and the level of persistent immune response, including some of the immune biomarkers associated with good therapeutic response such as CXCL10, FCRL3, and T cell receptor genes." (PMID 33815367, 2021). "A recent ongoing phase 2 study (NCT04896385), currently in the recruitment stage, aims to investigating the mechanism of action of ruxolitinib cream for the treatment of vitiligo by evaluating the changes in immune biomarkers, including CXCL10." (PMID 40136446, 2025). "The therapeutic potential of targeting this axis is highlighted by previous studies demonstrating that neutralization of CXCL10 not only prevents but also reverses depigmentation in murine vitiligo models." (PMID 40725033, 2025). "In agreement with the previous studies, our results also showed that the plasma levels of CXCL9 and CXCL10 are increased in vitiligo patients." (PMID 39981245, 2025). "To date, a number of clinical researches have reported that IFN-γ and its induced chemokines, CXCL9 and CXCL10, are related to disease activity, severity and prognosis in vitiligo." (PMID 39981245, 2025). "ELISAs showed that inflammatory cytokines associated with vitiligo, such as IFNγ, IL6, and CXCL10 were significantly elevated in CUMS serum." (PMID 40361040, 2025). "JAK inhibitors, for instance, have shown the ability to reduce CXCL9 and CXCL10 levels, effectively controlling vitiligo progression." (PMID 40136446, 2025). "In the model with one predictor, CXCL10 is the most effective factor to predict the recurrence of vitiligo, with AUC value of 0.896." (PMID 39981245, 2025). "The measurements revealed significantly higher levels of both IL-6 and CXCL10 in vitiligo patients compared to controls." (PMID 39337683, 2024). "In the pathogenesis of vitiligo, CXCL10 plays a crucial role in the initiation and maintenance of skin depigmentation." (PMID 39338414, 2024). "CXCL10 is raised both in the skin and serum of vitiligo patients, and CXCR3, its receptor, is expressed on pathogenic T cells." (PMID 39201060, 2024). "As relevant data, the highest values of CXCL10 were detected in patients with vitiligo versus controls, as well as in patients with disease of shorter duration (p < 0.05)." (PMID 37985303, 2024). "More recent meta-analysis data show that CXCL9, CXCL10, CCL5, CXCL8 (IL-8), CXCL12, and CXCL16 can serve as diagnostic blood biomarkers for vitiligo." (PMID 38673994, 2024).
vitiligo (continued). "On one hand, the increase in CXCL10 contributes to the development of vitiligo, and on the other hand, the presence of vitiligo leads to a significant upregulation of CXCL10 expression." (PMID 38660673, 2024). "The present data contribute to confirming the relevant role of the IFNγ/CXCL10 axis in the pathogenesis of vitiligo, highlighting CXCL10 as a possible activity marker." (PMID 37985303, 2024). "CXCL10 has been detected by many studies in the serum of vitiligo patients with expression levels well above the detection limits of standard enzyme-linked immunosorbent assays (ELISA) kits and multiplex bead arrays." (PMID 38715599, 2024). "This discovery aligns with previous studies, emphasizing CXCL10 as a potential effective target for treating vitiligo." (PMID 38660673, 2024). "It has also been demonstrated that IL-6 and CXCL10 are reliable markers of vitiligo activity status." (PMID 39337683, 2024). "CXCL9 and CXCL10 are expressed in many other skin diseases, and their functional importance was demonstrated for vitiligo, where inhibition of CXCL10 reduced recruitment of T cells and resulted in skin repigmentation." (PMID 39190494, 2024). "Serum CXCL9 (AA > vitiligo) and CXCL10 (AA = vitiligo) are elevated in both AA (N = 15) and vitiligo (N = 15) as compared with controls (N = 15)." (PMID 38673994, 2024). "The levels of IFN-γ were reported to be elevated in lesional skin of patients with vitiligo, which induced an increase of CXCL10 in vitiligo melanocytes." (PMID 36980277, 2023). "In the clinic, serum CXCL10 is representative of a specific biomarker that can monitor vitiligo activity and severity." (PMID 36980277, 2023). "The mean values of CXCL10 ranged from 21.5 pg/ml to 1619 pg/ml in healthy controls and 40.09 pg/ml to 916.9 pg/ml in vitiligo patients." (PMID 36911664, 2023). "In lesional skin and serum from vitiligo patients, the gene expressions of CXCL10 and CXCR3 are significantly upregulated." (PMID 36675078, 2023). "CXCL9 and CXCL10 levels were significantly higher in patients (active and stable groups) than controls, and among the vitiligo patients, CXCL9 and CXCL10 levels were significantly higher in active than stable groups." (PMID 37762802, 2023). "In both active and stable vitiligo, CXCL9 and CXCL10 were significantly higher than controls (p < 0.05), and they were significantly higher in active than stable vitiligo (p < 0.05)." (PMID 37762802, 2023). "Proinflammatory FB populations have been recently described in other inflammatory skin diseases, including Th2 responsive COL6A5+COL18A1+ FBs in atopic dermatitis and T cell–attracting CXCL9/CXCL10-expressing FBs in vitiligo." (PMID 37471168, 2023). "Of these chemokines, CXCL10 seems to display the most notable change in the blood circulation of vitiligo patients and is elevated in patients with active disease." (PMID 36911664, 2023). "12/15 studies (80%) reported significantly higher CXCL10 levels in vitiligo patients compared to controls, resulting in an overall highly significant CXCL10 concentration in the blood of vitiligo patients (P < 0.00001)." (PMID 36911664, 2023). "CXCL10 is thought to drive the autoimmune skin disease, vitiligo as well as function as a biomarker for progression of psoriasis." (PMID 37228128, 2023). "We further study the plasma expression of IFN-γ, CXCL9, CXCL10, and GzmB in active and stable vitiligo compared to healthy control." (PMID 35464413, 2022). "The results show that IFN-γ, CXCL9, CXCL10, and GzmB are highly expressed in the skin blister interstitial fluid and plasma of vitiligo compared to healthy controls." (PMID 35464413, 2022). "IFN-γ and its’ signature chemokines CXCL9 CXCL10 are critical in the pathogenesis of vitiligo for recruiting autoreactive cytotoxic T lymphocytes (CTLs)." (PMID 35464413, 2022).